PYHIN1 (pyrin and HIN domain family member 1)
Description:
Major mediator of the tumor suppressor activity of IFN in breast cancer cells. Promotes ubiquitination and subsequent degradation of HDAC1, which in turn enhances maspin expression, and impairs invasive activity of cancer cells.
Synonyms: IFIX; MGC23885
Tractability: PROTAC: ubiquitination databases record sites on it; its protein half-life has been measured.
Gene: Protein-coding gene on chromosome 1 (158,930,796 to 158,977,059, forward strand). Ensembl gene ENSG00000163564.
Subcellular location: Nucleus, nucleoplasm (Isoform 1); Nucleus, nucleoplasm (Isoform 3); Nucleus (Isoform 5); Nucleus speckle
Subcellular location (Human Protein Atlas): Nucleoli; Nucleoplasm
Gene Ontology:
Molecular function: ubiquitin protein ligase binding; double-stranded DNA binding
Biological process: cellular response to interferon-alpha; positive regulation of DNA binding; positive regulation of DNA-templated transcription; positive regulation of protein localization to nucleus; positive regulation of ubiquitin-dependent protein catabolic process; protein destabilization; protein stabilization; activation of innate immune response; cellular response to interferon-beta
Cellular component: nucleoplasm; protein-containing complex; cytosol; nucleolus; nuclear speck; nucleus
Genetic constraint (gnomAD): Loss-of-function variants: 31 observed, 40.89 expected, observed/expected ratio (o/e) 0.76, 90% interval 0.57 to 1.02. The upper end of that interval is the gene's LOEUF score, 1.02, which puts it in group 4 of 6, group 1 being the genes least tolerant of losing a copy. Missense variants: 563 observed, 590.45 expected, observed/expected ratio (o/e) 0.95, 90% interval 0.89 to 1.02. Synonymous variants: 199 observed, 203.04 expected, observed/expected ratio (o/e) 0.98, 90% interval 0.87 to 1.1.
Homologues: Orthologues: chimpanzee PYHIN1 (97% identical), macaque PYHIN1 (85% identical). Paralogues in human: IFI16 (65% identical), MNDA (43% identical), AIM2 (25% identical).
Diseases named in the same sentence as PYHIN1 in open-access papers:
PYHIN1 is named in the same sentence as 21 diseases in open-access papers, as found by Europe PMC text mining. Sharing a sentence is not in itself a finding about the gene and the disease. The quoted sentences say what the papers report.
asthma (10 papers, 2012 to 2022). "Other genes showed ethnicity-specific patterns, including PYHIN1, that were associated with asthma but only in persons of African ancestry." (PMID 36294997, 2022). "rs12125935 (p-value 2.78 × 10− 6) harbors PYHIN1, which encodes a protein involved in inflammasome activation in response to pathogens, and represents an asthma susceptibility locus specific to African-American ancestry." (PMID 31533690, 2019). "We were unable to assess the PYHIN1 variant reported as associated with asthma in African-Americans as this variant is monomorphic in European populations." (PMID 23028483, 2012). "A meta-analysis of genome-wide association studies correlated SNPs present in the PYHIN1 gene region with asthma in African-American and African-Caribbean populations, suggesting a possible link between this PYHIN protein and asthma pathogenesis." (PMID 32102850, 2020). "Asthma GWAS have identified a robust set of genes that are consistently associated with the disease in diverse populations (e.g. the IKZF3-ZPBP2-GSDMB-ORMDL3 locus, TSLP, and RORA), as well as genes that seem to be race/ethnicity specific (e.g. PYHIN1)." (PMID 23984888, 2013). "However, further analysis did not confirm the significant linkage between asthma-associated loci and PYHIN1 gene in individuals of African ancestry." (PMID 32102850, 2020).
viral infection (5 papers, 2020 to 2024). "While the relevance of PYHIN1 and MNDA in restricting viral infections in vivo remains to be determined, our results clearly demonstrate that they are about as effective as IFI16 in restricting HIV-1 in primary macrophages." (PMID 32760121, 2020).
breast cancer (4 papers, 2020 to 2025). A primary or metastatic malignant neoplasm involving the breast. "The latest member of the PYHIN family to be discovered was IFIX (also named PYHIN1) as a putative tumor suppressor gene in breast cancer." (PMID 33353088, 2020).
ovarian carcinoma (2 papers, 2020 to 2023). A malignant neoplasm originating from the surface ovarian epithelium. "Subsequently, to quantify the survival risk for each ovarian cancer patient, we developed a risk model utilizing a multi-factorial Cox formula based on the four aforementioned genes (WEE1, PYHIN1, SEC61A2, and HAL)." (PMID 37781709, 2023). "Our findings indicated that WEE1, PYHIN1, and SEC61A2 served as risk factors impacting the prognosis of ovarian cancer, while HAL demonstrated a protective effect." (PMID 37781709, 2023). "In certain cancer types, different eQTL-lncRNAs pairs influence the same set of mRNA targets; for example, in ovarian cancer, two eQTL (2p25.2 and 7q34) eventually regulate the same set of mRNAs (FASLG, GZMM, PYHIN1 and TRAT1) but through different elncRNAs (AC092580.4 and TRBV11-2)." (PMID 33194770, 2020).
breast tumors (1 paper, 2021). "PYHIN1 expression has been presented to be reduced in breast tumors." (PMID 34367961, 2021).
mycobacterial infections (1 paper, 2017). "Whether, other members of ALR genes in humans (PYHIN1 and MNDA) which also have PYHIN and HIN domains may play a role in innate immune response during mycobacterial infections, needs further investigation." (PMID 28529930, 2017).
tumor (12 papers, 2015 to 2025). "Pyrin and HIN domain family member 1 (PYHIN1) has the function of tumor suppression." (PMID 30867653, 2019). "Furthermore, we observed a significant positive correlation between the expression of the PYHIN1 gene and CD8+ T cells, suggesting that the PYHIN1 gene primarily influences changes in the tumor microenvironment by regulating the proliferation of cytotoxic T lymphocytes." (PMID 37781709, 2023). "PYHIN1, a member of the PYHIN (pyrin and HIN domain-containing) protein family, exerts complex functions ranging from tumor suppression to tumor promotion, depending on the specific tumor." (PMID 37781709, 2023). "The significant genes observed were PYHIN1, IKZF1, CASP8, DAPK1 and SMCHD1 expression in tumor samples." (PMID 30867653, 2019). "Similarly, PYHIN1 displayed significantly higher mRNA expression in tumor samples, although no significant protein staining." (PMID 37781709, 2023). "This group includes interferon-inducible protein 16 (IFI16), myeloid cell nuclear differentiation antigen (MNDA), absent in melanoma 2 (AIM2), and pyrin and HIN domain family member 1 (PYHIN1), each of which has been reported to be related to tumor progression." (PMID 37998338, 2023).
cancer (6 papers, 2017 to 2025). A tumor composed of atypical neoplastic, often pleomorphic cells that invade other tissues. "Our study suggests that monocyte-derived biomarkers, specifically WEE1, PYHIN1, SEC61A2, and HAL, hold potential as predictors for cancer prognosis and AMI." (PMID 37781709, 2023). "Most important of all, these findings demonstrate the potential of utilizing shared biomarkers (WEE1, PYHIN1, SEC61A2, and HAL) to predict outcomes in both cancer and AMI patients." (PMID 37781709, 2023). "At the same time, pan-cancer analysis also shows that PPM1A, DAPK1, FBP1, PYHIN1, ALPL and SMCHD1 have significant amplification in PCa." (PMID 30867653, 2019). "In summary, our findings suggest that WEE1, PYHIN1, SEC61A2, and HAL derived from monocytes may serve as a potential predictor for AMI and cancer prognosis." (PMID 37781709, 2023). "However, further experimental studies are needed to elucidate the specific roles of WEE1, PYHIN1, SEC61A2, and HAL in disease occurrence, progression, and response to treatment in both cancer and AMI." (PMID 37781709, 2023). "In our study, our findings suggest that WEE1, PYHIN1, SEC61A2, and HAL derived from monocytes may serve as a potential predictor for AMI and cancer prognosis." (PMID 37781709, 2023).
infection (4 papers, 2013 to 2021). The state of being infected such as from the introduction of a foreign agent such as serum, vaccine, antigenic substance or organism. "PYHIN1 and IFI16 have recently emerged as sensors of microbial DNA, and the innate immune response relies on the ability of immune cells to detect the presence of infection through these germline-encoded pattern recognition receptors." (PMID 24324648, 2013). "Despite moderate kd efficiencies, reduced IFI16 and PYHIN1 expression increased infectious virus yield of CCR5-tropic HIV-1 AD8, which is capable of spreading infection in macrophages, on average by ~6.4-fold at 3 dpi and ~21.6-fold at 6 dpi." (PMID 32760121, 2020).
PYHIN1 also shares sentences with these, for which no sentence is quoted: oral cancer (2 papers); oral squamous cell carcinoma (2); autism (1); heart failure (1); herpesvirus infection (1); influenza (1); invasive carcinoma (1); lymph node metastasis (1); papilloma (1); promyelocytic leukemia (1); tongue squamous cell carcinoma (1); ZIKV infection (1).